CYP11A1 (cytochrome P450 family 11 subfamily A member 1)
Diseases named in the same sentence as CYP11A1 in open-access papers (continued):
Sharing a sentence is not in itself a finding about the gene and the disease.
melanoma (13 papers, 2014 to 2026). A malignant, usually aggressive tumor composed of atypical, neoplastic melanocytes. "In the B16-F10 subcutaneous melanoma model, topical application of exogenous pregnenolone at the primary tumor site was sufficient to compensate for the Cyp11a1 deficiency, restoring tumor growth to levels comparable with control mice." (PMID 32680985, 2020). "We show that lung colonization of melanoma nodules was markedly diminished in mice with mast cell-specific ablation of Cyp11a1, accompanied by reduced infiltration of mast cells into the lungs." (PMID 42230785, 2026). "Recent discoveries in the CYP11A1-dependent vitamin D metabolic pathway offer promising new therapeutic targets for melanoma prevention and treatment." (PMID 40331942, 2025). "In past studies, CYP11A1-derived 20(OH)L3, 22(OH)L3, 24(OH)L3 and 20,22(OH)L3 were shown inhibit the proliferation of human melanoma cells (SKMel-188)." (PMID 39456696, 2024). "Our previous studies show that novel CYP11A1-derived vitamin D derivatives inhibit proliferation of different cells, including melanoma." (PMID 34206371, 2021). "To explore Cyp11a1 expression in vivo, we utilized the well-established B16-F10 melanoma model and implanted tumors subcutaneously in Cyp11a1-mCherry reporter mice." (PMID 32680985, 2020). "CNA data demonstrate that the CYP11A1 gene was amplified at ~1.5%, ~1.4%, ~3%, ~1.6%, and ~1.1% in breast, melanoma, ovarian, pancreatic, and uterine endometrial cancers, respectively." (PMID 31060224, 2019). "The CYP11A1-derived hydroxylumisterols inhibit skin cell proliferation in a cell-type dependent fashion with pronounced effects on keratinocytes, and show anti-melanoma activity as well." (PMID 28900196, 2017). "In conclusion, we provided in vitro and in vivo evidence that the CYP11A1-derived 20(OH)D3 is an excellent candidate for further testing as a primary or adjuvant therapeutic agent against human melanoma." (PMID 28039464, 2017). "Previously, we found that decreased expression of VDR and CYP27B1 are associated with progression of melanoma and decreased overall and disease-free survival of melanoma patients, and that novel CYP11A1-derived forms of vitamin D have anti-melanoma activity." (PMID 25334067, 2014). "However, the regulation and role of IL-17 are complex, including regulation of IL-17 in melanoma by CYP11A1-derived vitamin D3 hydroxyderivatives and transcriptional regulation of IL-17 by RORγ." (PMID 38927967, 2024). "CYP11A1 is also expressed in normal melanocytes and melanoma cells, so these cells can potentially carry out the CYP11A1-initiated pathways of vitamin D metabolism, with subsequent modification of products by CYP27B1, CYP24A1, or CYP27A1, which are also expressed in melanoma cells." (PMID 38927967, 2024). "A variety of vitamin D3 and D2 derivatives were tested including classical forms, chemically generated low calcemic forms, and CYP11A1-derived non-calcemic or low calcemic variants, all of them showing anti-melanoma activities on cultured melanoma cells." (PMID 38927967, 2024). "The finding of unexpected expression patterns of CYP24A1 in melanoma proposed that, in context of the dominant CYP11A1-driven alternative vitamin D metabolism pathway in the skin, CYP24A1 can produce biologically active tumor-suppressive vitamin D metabolites rather than degrading calcitriol." (PMID 29657326, 2018). "Following our previous findings that CYP11A1-derived hydroxysecosteroids can inhibit proliferation of melanoma cell lines, we selected 20(OH)D3 for further experimental testing on a SKMel-188 human melanoma line using established in vitro and in vivo assays of tumorigenesis and tumor progression." (PMID 28039464, 2017). "In addition, CYP11A1-derived lumisterol hydroxy metabolites inhibited melanoma proliferation." (PMID 38927967, 2024). "Human melanoma tissues represented a prominent steroidogenic tumor type, expressing CYP11A1, HSD3B1, HSD3B2, CYP17A1, CYP21A1, and CYP11B1 and not expressing CYP11B2." (PMID 32680985, 2020).
melanoma (continued). "Interestingly, 20(OH)D produced by CYP11A1 can be hydroxylated by CYP24A1 to 20,24(OH)2D and 20,25(OH)2D, which are more potent in suppressing melanoma growth than calcitriol and 20(OH)D165." (PMID 29657326, 2018). "On the other hand, the expression of VDR and its splicing variants and other vitamin D related genes (RXR, PDIA3, CYP3A4, CYP2R1, CYP27B1, CYP24A1 and CYP11A1) was detected in WM98 and A375 melanomas with the transcript levels being modulated by vitamin D analogs." (PMID 30200275, 2018). "Finally, the mRNA level of CYP27B1 was not affected by vitamin D analogues and CYP11A1 was elevated in A375 melanoma cells only after treatment with calcipotriol." (PMID 30200275, 2018). "The major CYP11A1-derived hydroxyderivatives can also be metabolized by CYP24A1, which catalyzes their hydroxylation at C24 or C25, and can increase their potency rather than decrease it, at least for inhibition of melanoma cell proliferation." (PMID 38927967, 2024).
prostate carcinoma (12 papers, 2015 to 2025). A carcinoma that arises from epithelial cells of the prostate gland. "Similarly, increased methylation of CYP11A1 has been linked to the development of prostate cancer recurrences." (PMID 39858027, 2025). "Cytochrome P450 family 11 subfamily A member 1 (CYP11A1) plays an important role in the recurrence and metastasis of prostate cancer." (PMID 40868150, 2025). "A study on the genomic relationship between CYP11A1 and prostate cancer using The Cancer Genome Atlas revealed that CYP11A1 was significantly downregulated in prostate cancer." (PMID 37435458, 2022). "Analysis of the same dataset revealed that bone-metastatic CRPC tumor samples exhibited higher expression levels of two key steroidogenic enzymes, AKRIC3 and CYP11A1, than that in primary prostate cancer." (PMID 32226548, 2020). "Since 20-OH cholesterol had relatively low turnover to downstream androgens, it is likely that the side chain cleavage enzyme (CYP11A1) has limited functionality in these prostate cancer cell lines." (PMID 30241348, 2018). "We next sought to determine whether the up-regulation of the two androgen biosynthetic enzyme genes AKR1C3 and CYP11A1 could be the result of direct targeting of ERRα in prostate cancer cells." (PMID 32226548, 2020). "Since the expression of CYP11A1 is rather low in prostate cancer cells and hardly detectable in clinical prostate cancer tissues, we next manly investigated the significance of ERRα-enhanced AKR1C3 expression or activity in the DHT biosynthesis in AR-positive prostate cancer cells." (PMID 32226548, 2020). "For prostate cancer cell lines PC-3, LNCaP and DU-145 it was observed that DON treatment induced an increase in CYP11A1 protein expression." (PMID 34678978, 2021).
preeclampsia (10 papers, 2013 to 2024). Preeclampsia is a hypertensive disorder of pregnancy that is characterized by new-onset hypertension with proteinuria presenting after 20 weeks of gestation, and depending on mild or severe forms may initially present with severe headache, visual disturbances, and hyperreflexia. "CYP11A1 has been identified as a candidate pathogenic gene for preeclampsia and shown to be hypomethylated and transcribed at higher levels in women with preeclampsia." (PMID 33659272, 2020). "Our previous studies have demonstrated that upregulation of CYP11A1 induces trophoblast apoptosis and is positively correlated with liver damage during preeclampsia; however, the underlying mechanism remains elusive." (PMID 33659272, 2020). "In this study, we investigated the exact mechanism by which excessive CYP11A1 expression impairs the placentation process and whether this causes preeclampsia (PE) in an in vivo model." (PMID 29163791, 2017). "The increase in CYP11A1 levels has been reported to be associated with the increase in the levels of an autophagy marker, LC3, during the pathogenesis of preeclampsia." (PMID 38036976, 2023). "Other work has shown that CYP11A1 protein is upregulated in the placenta of women with preeclampsia and overexpression of CYP11A1 protein in human trophoblast cells reduces proliferation and induces apoptosis." (PMID 35293971, 2022). "In conclusion, our previous study had shown that CYP11A1 overexpression can induce preeclampsia and compromise placental development in rats." (PMID 35002603, 2021). "Our previous study using a rat model of CYP11A1 gene overexpression showed that the treated dams developed preeclampsia-like symptoms." (PMID 35002603, 2021). "In our previous study, we found that CYP11A1 gene expression was significantly increased in the placenta during severe preeclampsia compared with that in normal pregnancies." (PMID 35002603, 2021). "In line with increased expression of CYP11A1 during preeclampsia, the level of pregnenolone (and progesterone) is increased in preeclamptic women." (PMID 30258364, 2018). "CYP11A1 is upregulated at both mRNA and protein level in placentas of women with severe preeclampsia." (PMID 30258364, 2018). "We had previously reported that overexpression of the mitochondrial cholesterol side-chain cleavage enzyme (CYP11A1) could lead to both preeclampsia-like symptoms and increased testosterone levels in pregnant rats." (PMID 35002603, 2021). "We had previously shown that placental CYP11A1 expression was increased in patients with preeclampsia and that the overexpression of this enzyme could lead to the apoptosis of placental trophoblasts." (PMID 35002603, 2021). "In another study, we showed that CYP11A1 overexpression induced preeclampsia-like symptoms in rats." (PMID 35002603, 2021). "Based on results obtained in isolated placental mitochondria and JEG-3 cells, it has been speculated that not only excess progesterone synthesis but also production of lipid peroxides by increased expression of placental CYP11A1 may contribute to the pathogenesis of preeclampsia." (PMID 30258364, 2018). "Some of the identified differently expressed genes include genes related to steroid metabolism, such as the cholesterol monooxygenase (CYP11A1) or hydroxysteroid 17β–dehydrogenase 1 (HSD17B1), highlighting the importance of steroid metabolism in preeclampsia." (PMID 39684415, 2024). "Significant DNA hypomethylation was observed in preeclampsia for steroidogenic genes, including CYP11A1 for cytochrome P450scc and HSD3B1 for 3β-hydroxy-delta-5-steroid dehydrogenase type 1, each controlling the two-step pathway of progesterone synthesis from cholesterol." (PMID 26068234, 2015). "Maternal progesterone, but not estrogen, concentrations are increased in women with preeclampsia and both steroid hormones positively stimulate CYP11A1 and HSD3B1 expression in trophoblast cells." (PMID 23667551, 2013).
Infertility (9 papers, 2017 to 2024). "Previous studies have documented an association between the decline in levels of CYP11A1 gene expression and testosterone production in aging Leydig cells and infertility." (PMID 39334937, 2024). "Here, we intend to examine the occurrence of polymorphisms in the CYP11A1 gene that increases PCOS risk with infertility." (PMID 35205347, 2022). "Because each individual’s SNP profile is unique, more investigations in various populations are required to resolve the controversy surrounding the effect of CYP11A1, CYP17A1, and CYP19A1 polymorphisms on infertility and PCOS." (PMID 35205347, 2022). "We evaluated the occurrence of polymorphisms in various ethnicities in the CYP11A1, CYP17A1, and CYP19A1 genes and their efficacy on increasing PCOS risk with infertility." (PMID 35205347, 2022). "We have chosen the genetic polymorphism of the genes involved in the steroidogenesis pathway as the candidate genetic variants that are susceptible to infertility between females with PCOS, focusing on CYP11A1, CYP17A1, and CYP19A1." (PMID 35205347, 2022). "In conclusion, our study strongly suggests that the CYP11A1, CYP17A1, and CYP19A1 genes might significantly enhance the probability of developing PCOS with infertility." (PMID 35205347, 2022).
primary adrenal insufficiency (9 papers, 2017 to 2026). A hormonal disorder that occurs when the adrenal glands fail to release adequate amounts of glucocorticoids (cortisol), mineralocorticoids (aldosterone, 11-deoxycorticosterone), and androgens (dehydroepiandrosterone) to meet physiologic needs, despite release of ACTH from the pituitary. "CYP11A1 mutations are associated with primary adrenal insufficiency (PAI) as well as disorders of sex development (DSD) in 46,XY patients." (PMID 30233493, 2018). "CYP11A1 (P450scc) deficiency is a rare and complex disorder that leads to primary adrenal insufficiency and may present with 46, XY disorders of sex development (DSD), phenotypic variations, and associated endocrinological abnormalities." (PMID 39457196, 2024). "Importantly, the findings from the urinary steroid profiling analysis were instrumental in excluding other causes of primary adrenal insufficiency (i.e. mutations in NR5A1, StAR, CYP11A1 or HSD3B2)." (PMID 34524979, 2021).
Obesity (7 papers, 2017 to 2026). Accumulation of substantial excess body fat. "We observed significant upregulation of genes such as Cyp11a1, Fdx1, Flt1, Gm2a, and S100a6 in the G05 subpopulation under the influence of obesity." (PMID 38956667, 2024).
hyperandrogenism (6 papers, 2022 to 2025). Excessive secretion of androgens from the adrenal glands or gonads. "Additionally, a strong association between follistatin and the Cytochrome P450 Family 11 Subfamily A Member 1 (CYP11A1) gene in affected siblings with hyperandrogenism and PCOS related traits was predicted by studying 37 candidate genes." (PMID 35787810, 2022). "Furthermore, increased levels of CYP11A1 are also correlated with hyperandrogenism and PCOS." (PMID 38275408, 2024).
hypospadias (6 papers, 2017 to 2024). Hypospadias is the displacement of the urethral meatus on the ventrum of the penis. "The moderate and severe hypospadias groups had too few genes for this analysis, but both did show links with CYP11A1 and CYP1A1 involved in steroidogenesis of androgen." (PMID 36631595, 2023). "Moreover, three studies found that key enzymes involved in testosterone synthesis, represented by Cyp11a1, Cyp17a1, Hsd3b, Scarb1, Star, Hsd17b3 and Srd5α2, were significantly reduced at the genetic level in DBP- or DEHP-induced hypospadias male fetal rats." (PMID 39698037, 2024).
colorectal cancer (5 papers, 2007 to 2025). A primary or metastatic malignant neoplasm that affects the colon or rectum. "No amplification of the CYP11A1 gene was observed in prostate and colorectal cancers." (PMID 31060224, 2019).
gastric cancer (5 papers, 2017 to 2025). A primary or metastatic malignant neoplasm involving the stomach. "In gastric cancer (GC), the interaction between CYP11A1 and cytotoxin-associated gene A redistributed mitochondrial CYP11A1 to the outside of the mitochondria." (PMID 40868150, 2025). "The most shared rewiring hubs are BUB1B (brain, lung-adeno, kidney-clear, kidney-papillary and stomach cancer), CYP11A1 (bladder, brain, kidney-clear and uterus cancer) and CCNB1 (brain, kidney-papillary, lung-adeno and lung-squamous cancer)." (PMID 31396397, 2019).
glucocorticoid deficiency (5 papers, 2016 to 2026). "Furthermore, partial inactivating mutations in CYP11A1 have been implicated in development of an isolated glucocorticoid deficiency." (PMID 38189052, 2023). "Investigations revealed isolated glucocorticoid deficiency, and WES yielded compound heterozygous variants in the CYP11A1 gene (c.940G > A; p.Glu314Lys and c.359G > A; p.Arg120Gln)." (PMID 41541841, 2026). "This case describes the follow up of a boy with PAI, presenting as isolated glucocorticoid deficiency with small adrenals, possibly due to tri-allelic inheritance of two STAR mutations and the rs6161 CYP11A1 variant." (PMID 35418949, 2022). "Here we report long-term follow up of a boy with PAI presenting as isolated glucocorticoid deficiency possibly due to tri-allelic inheritance of variants in STAR and CYP11A1." (PMID 35418949, 2022). "This combination of findings raises the possibility that a non-classical congenital (lipoid) adrenal hyperplasia is the cause of isolated glucocorticoid deficiency in this patient due to combined digenic, tri-allelic inheritance of two STAR mutations and the rs6161 CYP11A1 variant." (PMID 35418949, 2022). "Based on the presence of a micropenis and the later onset of hyperpigmentation, along with failed ACTH stimulation test and XY karyotype, we suspected the diagnosis of mutations of NR0B1, CYP11A1, and STAR genes or familial glucocorticoid deficiency (FGD) (MC2R, MRAP, NNT, and AAAS)." (PMID 36407315, 2022). "FGD can present with salt loss suggestive of adrenal hypoplasia, and alterations in STAR and CYP11A1 resulting in partial loss of protein function may have a predominant FGD-like phenotype, with glucocorticoid deficiency without genital abnormalities in 46,XY newborns." (PMID 27485500, 2016).
adrenocortical cancer (4 papers, 2012 to 2025). "As experimental control, we used again Y1 adrenocortical cancer cells, where Nr5a1 gene down-regulation caused a reduction of Cyp11a1 mRNA expression." (PMID 23756599, 2013). "Our studies show that Cyp11a1 plays a pro-proliferative role in adrenocortical cancer and PA cells, thereby providing additional evidence supporting a role for this gene in tumorigenesis." (PMID 23756599, 2013). "Here we show that Cyp11a1 plays a pro-proliferative role in Y1 adrenocortical cancer cells, but also in GH3 somatotroph adenoma cells and in rat primary pituitary gonadotroph cells." (PMID 23756599, 2013). "In conclusion, high expression of Cyp11a1 associates with increased proliferation and survival not only in adrenocortical carcinoma cells (Y1), but also in rat pituitary tumor cells from different lineages (somatotroph and gonadotroph)." (PMID 23756599, 2013).
COVID-19 (4 papers, 2022 to 2023). A disease caused by infection with severe acute respiratory syndrome coronavirus 2. "In addition to targeting COVID-19 through both nuclear receptor-dependent and-independent mechanisms, new CYP11A1-derived active forms of vitamin D and lumisterol can be used as antiviral drugs and supplements to prevent and attenuate it." (PMID 36829806, 2023).
endometriosis (4 papers, 2018 to 2025). The growth of functional endometrial tissue in anatomic sites outside the uterine body. "When comparing eutopic and ectopic tissue from endometriosis patients, more cell types express CYP11A1, hinting towards PS (and DHEAS) in endometriosis pathophysiology." (PMID 41154581, 2025). "Next, we assessed whether the expression levels of CYP11A1 and CYP17A1 in the endometriosis lesion correlates with the concentrations in the peritoneal fluid of the respective neurosteroids they produce (i.e., PS and DHEAS)." (PMID 41154581, 2025). "AEBP1 and HOXB6, together with IGF-1, CYP11A1, MMP-2, CC2D2A, IER3, STX18, maybe staging markers for endometriosis." (PMID 36532015, 2022). "A few studies reported detectable levels of the enzymes involved in the generation of DHEA from cholesterol (StAR, CYP11A1 and CYP17A1) in endometriosis, suggesting that, in contrast to eutopic endometrium, endometriosis is able to produce steroids from cholesterol." (PMID 30283331, 2018).
Insulin resistance (4 papers, 2016 to 2025). Increased resistance towards insulin, that is, diminished effectiveness of insulin in reducing blood glucose levels. "Quercetin, a flavonoid found in P. dioscoridis extract, increases CYP19A1 and CYP11A1 expressions leading to elevating estrogen levels in letrazole-induced PCOS mice model, in addition to improving insulin resistance through its antioxidant properties." (PMID 40569946, 2025).